CLDN1 (claudin 1)
Diseases named in the same sentence as CLDN1 in open-access papers (continued):
Sharing a sentence is not in itself a finding about the gene and the disease.
infection (continued). "A key contribution of this study is the demonstration of AZM in enhancing barrier integrity by increasing the expression of key TJ proteins, specifically claudin-1 and occludin, following HRV-1b infection." (PMID 40641604, 2025). "Barrier functions genes such as CLDN1 (Claudin 1) and JAM3 (Junctional Adhesion Molecule 3) were significantly upregulated in response to infection in both jejunum and caecum." (PMID 40500794, 2025). "Both routes of infection require expression of the receptor complex (CD81, scavenger receptor BI, claudin-1 and occludin)." (PMID 37750869, 2023). "On d 8 (peak infection), CQ30 birds exhibited a significantly greater abundance of CLDN1 and CLDN5 (p = 0.0016 and p = 0.0038, respectively) compared to NC and PC, as well as AMPK compared to all other treatments." (PMID 37630454, 2023). "HCVpp were crucial in the identification of CLDN1 and OCLN as HCV entry factors (39, –, 41) and the determination of epitopes that are targeted by neutralizing antibodies during infection (42, –, 44)." (PMID 37310242, 2023). "Our previous studies showed that the mRNA expression levels of tight junctions including claudin-1, claudin-3, claudin-7, and claudin-11 were up-regulated with AKG supplementation after infection with A. hydrophila." (PMID 35720284, 2022). "In Huh7.5 cells, TACSTD2 interacts with CLDN1 and OCLN and effectively activates PKC-mediated phosphorylation of CLDN1 and OCLN, which is required for their proper cellular localization, and in order to facilitate the infection of HCV." (PMID 36297257, 2022). "Compared to mock-infected groups, Claudin 1 (CLDN1) and CLDN4 were significantly upregulated, while CLDN8 and Occludin (OCLN) were downregulated in the HP-PRRSV infection group." (PMID 35336858, 2022). "During early HPS5-SQ infection, autophagy cutting off cell membrane Claudin-1 replenishment disrupted STEC cytoplasmic Claudin-1 and breached the porcine airway epithelial barrier by injuring paracellular." (PMID 36228044, 2022). "In the infection of HPS5-SQ or pretreated with CCCP for 6 and 12 h, Claudin-1 and Parkin level in STEC was downregulated, and EGFP-Claudin-1 expression was quickly diminished." (PMID 36228044, 2022). "Consistent with in vitro results, PEDV intranasal infection resulted in considerable degradation of ZO-1, OCLN, and CLDN-1 in nasal microvessels." (PMID 35435723, 2022). "CLDN1, CLDN6, and CLDN9 usages on HCVpp infection were previously reported in other genotypes than genotype 2a, which HCV-JFH1 belongs to22,23." (PMID 36424447, 2022). "Claudin 1 (CLDN1) supports intercellular barrier function of tight junctions, and mucin 1 (MUC1) is located on the cell surface to provide a barrier to infection." (PMID 35202261, 2022). "The expression of N-cadherin was decreased, whereas Claudin-1, ZO-1, and E-cadherin levels were increased, after SRI-shRNA infection in OV3R-PTX cells and an opposite effect was observed after overexpression of SRI in OVCAR-3 cells." (PMID 34163033, 2021). "Upon flavividae infection, BBB and TJ are often disrupted: infection with West Nile virus and classic swine fever virus both lead to claudin-1 degradation and Japanese encephalitis virus infection induces the degradation of claudin-5." (PMID 34616388, 2021). "In this study, NE infection remarkably downregulated occludin and ZO-1 mRNA levels, while the NE-infected birds fed BLJ showed upregulated claudin-1 mRNA expression levels in the jejunum compared with those of untreated NE-infected birds." (PMID 32110391, 2020). "Interestingly, pre-treatment of OE-TLR3(-) cells with IFN-β prior to infection appeared to mildly but significantly increase the synthesis and stability of claudin-3 at the 20hr time point, while substantially bolstering the synthesis and stability of claudin-1 and claudin-2 throughout infection." (PMID 30625140, 2019).
infection (continued). "This has been demonstrated for HIV-1 co-receptors CCR5 and CXCR4, the poliovirus receptor, the HCV receptor molecules CD81, occluding (OCLN) and claudin-1 (CLDN1), and the AXL receptor for Zika virus in HeLa cell infection." (PMID 29361752, 2018). "In the present study, treatment with curcumin and infection with RSV, downregulated p63 and upregulated CLDN-1 and CLDN-4, and CLDN-4 and OCLN, respectively, in HNECs." (PMID 28883651, 2017). "In this review we summarize the main results emphasizing the relationship in terms of membrane partitioning between tetraspanins, some of their partners such as Claudin-1 and EWI-2, and viral proteins during infection." (PMID 24800676, 2014). "Synchronized infection assays showed that glycosaminoglycans and SR-BI mediated host cell binding, while CD81, CLDN1 and OCLN all acted sequentially at a post-binding stage prior to endosomal acidification." (PMID 23555257, 2013). "The remaining antibodies targeting CD81, CLDN1, and OCLN all continued to strongly inhibit infection when added after the binding phase, indicating these factors are post-binding HCV cell entry factors." (PMID 23555257, 2013). "On the other hand, knockdown of CLDN1, TJP1, CD63, 14-3-3 β, and GLUT4 reduced HCV RNA level more than 50% at 12 hrs post infection." (PMID 23593195, 2013). "We found that antibodies targeting CD81, CLDN1, and the OCLN EC2-F5 mutant blocked infection when added either pre- or postbinding, indicating that these agents block postbinding HCV cell entry events." (PMID 23555257, 2013). "Knockdown of CD63, as well as that of the positive control CLDN1, reduced HCV RNA level more than 50% at 6 hrs post infection." (PMID 23593195, 2013). "HCV mainly targets hepatocytes and its infection is mediated by several entry cofactors located on the cell surface, including the tetraspanin CD81, the scavenger receptor class B member I (SR-BI), Claudin 1 (CLDN1), and Occludin (OCLN)." (PMID 23202463, 2012). "HCV envelop protein E2 posses glycosylation sites which interact directly with the cell surface receptors CD81, SR-BI and CLDN1, confirming their role in HCV entry by using HCVpp or HCVcc infection in liver cell lines." (PMID 21896165, 2011). "The permeability, the distribution and expression of tight junction proteins (such as Claudin-1, Occludin, JAM-1 and ZO-1) and the cytoskeleton were examined when infected with EIEC or adhesived of L. plantarum after infection." (PMID 19331693, 2009). "By contrast, unlike wild-type C. albicans, direct infection with the Cacfl11Δ mutant did not markedly affect the expression of CLDN1 or JAM1." (PMID 41590450, 2026). "After infection with E. coli K99, the expression of P. pentosaceus SNF15, Claudin-1, MUC2, and ZO-1 in oral administration increased significantly compared with the CN group (p < 0.05), and the expression level of occludin did not change significantly (p > 0.05)." (PMID 40151573, 2025). "However, elevated expressions of mRNA and protein of claudin-1, VCAM, and E-selectin were observed post-infection." (PMID 38073104, 2024). "Overall, infection with Aa or Sg downregulated the transcription of these genes, whereas infection with both organisms in the Aa+Sg group increased their mRNA levels, similar to the levels of the SHAM group, except for Cldn1, which achieved lower mRNA levels in Aa and Aa+Sg groups." (PMID 39125663, 2024). "We found that GBVBpp could infect CLDN1 with EL1 replaced with that of CLDN9 (ChimB), but infection fell below the limit of detection when EL2 was swapped (ChimA), suggesting that the C-terminal region containing EL2 of CLDN1 is critical for GBV-B entry." (PMID 37310242, 2023). "In contrast, VD3 sufficient addition remarkably up-regulated the protein levels of Claudin-4 as well as ZO-1 (P < 0.05) and trended to increase the Claudin-1 protein amount (P = 0.061) regardless of infection." (PMID 35619956, 2022).
infection (continued). "Still, the altered expression of tight junction proteins was not restricted to claudin-1 as we also detected ZO-1 throughout the cytoplasm in dsRNA(+) cells without any change in overall protein levels during infection." (PMID 34995322, 2022). "In a previous study with orally E. coli 536-infected germ-free mice, claudin-1, -2 and -3 expression in the colonic mucosa was not changed even 3 days after infection." (PMID 34437391, 2021). "VD inhibited the C. jejuni-induced changes in claudin-1 expression, which also does not explain the changes in the barrier function induced by infection." (PMID 34445577, 2021). "In contrast, compared with infection groups, AKG supplementation could significantly upregulate the gene expression levels of claudin-1 and claudin-3, and as well as the mRNA level of claudin-7 and claudin-11 (P < 0.05)." (PMID 34220849, 2021). "In addition, by 7 days after infection, although weights were recovering, EPEC-infected mice had increased intestinal permeability and decreased colonic claudin-1 levels." (PMID 33392105, 2020). "In addition, a significant interaction effect on claudin-1, IGF-2 and mucin-2 mRNA expressions occurred between NE infection and BLJ addition." (PMID 32110391, 2020). "Pretreatment with E. faecium notably upregulated CLDN-1 mRNA levels and protein content in the jejunum mucosa of birds, regardless of NE infection." (PMID 31311959, 2019). "In contrast, claudin-1 transcription was not as affected early during infection in the OE-TLR3(-) cells, and its expression levels were 3-fold lower than the OE129-WT cells at the 36hr time-point." (PMID 30625140, 2019). "Taken together, the data indicate that high affinity cCPE-SSS binding to Cldn1 is efficiently inhibiting HCV infection of Huh7.5 cells whereas high affinity cCPEwt binding to Cldn6 is not sufficient to inhibit the infection efficiently." (PMID 31561440, 2019). "Four cell-surface molecules, CD81, occludin (OCLN), claudin 1 (CLDN1), and scavenger receptor class B member 1 (SRB1), are particularly important for HCV cell entry, although only CD81 and OCLN determine the species-specificity of infection." (PMID 29765366, 2018). "It was also found that an infection with EPEC reduced significantly the TJ proteins (occludin (phosphorylated form), ZO-1 and claudin-1), which is supported by other findings reporting a rapid and progressive dephosphorylation of occludin following EPEC infection." (PMID 28208612, 2017). "In addition, infectious titers in the culture supernatants at 72 h post-infection exhibited little decrease in SR-KO cells, in contrast to the much greater decreases in CD81, CLDN1 or OCLN KO Huh7 cells." (PMID 27152966, 2016). "The distribution of CLDN1 expression (or any entry receptor) would remain unchanged post-infection on such cells if there were no explicit modulation by HCV over times short compared to the average life span of infected cells." (PMID 22545157, 2012). "The overexpression of claudin-1 in cell lines permissive to HCVpp infection did not enhance infectivity." (PMID 19643019, 2009). "HCVpp infection remained CD81 dependent even when claudin-1 was overexpressed in Hep-G2 (CD81 negative cell line, becomes susceptible to HCVpp upon expression of CD81) cell line." (PMID 19643019, 2009). "In the current study, FML upregulated the expression of intestinal barrier genes in the duodenum (MUC 1) and ileum (claudin 1 and claudin 2), suggesting that FML enhances the integrity of the mucous layer and generates a host-friendly gut environment to defend against pathogen infection." (PMID 39409860, 2024). "However, the specific mechanism by which CLDN1 expression increases during NE infection in chickens is not yet fully understood." (PMID 37799512, 2023). "Although TJP genes are typically downregulated during infection, one study suggests that the upregulation of CLDN1 may not universally indicate increased barrier function." (PMID 37799512, 2023).
infection (continued). "Meanwhile, dietary EOA treatment also upregulated CLDN-1, OCLN, ZO-1, MUC2 and FABP2 mRNA levels at the middle infection phase, as well as linearly reduced the gene expression level of TLR4, NF-κB and IL-1β at the early infection stage in infected broiler chickens." (PMID 37391807, 2023). "On day 7 post-infection both PD-1 and IL-17A demonstrated higher scores in the intestine of diabetic-untreated mice compared with non-diabetics and healthy control; whereas, claudin-1 revealed worsening expression." (PMID 37719029, 2023). "At 10 d PI, only CLDN1 was not affected by either infection or feed type." (PMID 33652244, 2021). "On 10 d PI, CLDN1 was not affected by either infection or feed." (PMID 33652244, 2021). "More specifically, as an immunomodulatory nutrient, glutamine regulate tight junction proteins (occludin, claudin-1, and zona occludens-1), controls chain reactions of cytokines such as TNF-α and IL-17A, and increases local secretory IgA (sIgA) production for preventing infection." (PMID 33143293, 2020). "Intriguingly, monoclonal antibodies against CLDN1 were shown to inhibit HCV entry, cell-cell-transmission and virus-induced signaling events in absence of detectable toxicity, and they were also effective in hindering infection by all major HCV genotypes and quasispecies." (PMID 29616082, 2018). "This may suggest that CLDN-1 might be dispensable for infection of not only lymphocytes but also some non-lymphoid cells." (PMID 23626783, 2013). "While AZM decreased claudin-1 gene expression in non-infected cells, it increased claudin-1 and occludin expression following HRV-1b infection." (PMID 40641604, 2025). "Two amino acids in extracellular loop 1 (EL1) of CLDN1, previously identified as being essential for HCV entry, have no impact on GBVBpp infection." (PMID 37310242, 2023). "CLDN1 KO cells were transduced to express mammalian CLDN1; armadillo and guinea pig CLDN1 did not support HCV J6pp entry, while rabbit and marmoset CLDN1 allowed infection." (PMID 37310242, 2023). "A multi-passaged HCV-JFH1-tau lot was infectious to CLDN1-defective S7-A cells, non-permissive to original HCV-JFH1-tau infection." (PMID 36424447, 2022). "Claudin-1 and HSP70 protein expression were also increased in the jejunum regardless of NE infection." (PMID 31311959, 2019).
liver (11 papers, 2013 to 2024). "In conclusion, our review indicates that selected CLDNs, particularly CLDN1, 2, 4, 7, and 18, play a significant role in the development of GI tumours and in patient prognosis." (PMID 38201579, 2023). "Our review indicates that selected CLDNs, particularly CLDN1, 2, 4, 7, and 18, play a significant role in the development of GI tumours and in patient prognosis." (PMID 38201579, 2023). "The downregulation of the tight junction proteins ZO-1, Occludin, and Claudin-1 can lead to the destruction of tight junction structures and an increase in cell bypass permeability, leading to LPS translocation to the liver and blood circulatory system and liver inflammation and injury." (PMID 37836761, 2023). "Therefore, we examined whether inflammation plays an important role in claudin-1-dependent upregulation of colon carcinogenesis." (PMID 24997475, 2014). "Claudin-1 is involved in the β-catenin- T-cell Factor/ Lymphoid Enhancing Factor signaling pathway, and increased expression of claudin-1 may be a component of colorectal tumorigenesis." (PMID 23919729, 2013). "We recently reported that claudin-1 (CLDN1) and CLDN2, components of tight junctions (TJs), decrease chemosensitivity to doxorubicin (DXR) in 3D-cultured A549 cells established from human lung adenocarcinoma." (PMID 30310131, 2018).
adenocarcinoma (10 papers, 2012 to 2023). A common cancer characterized by the presence of malignant glandular cells. "The authors demonstrated that CLDN-1 overexpression inhibited adenocarcinoma cell dissociation in wound-healing time-lapse images." (PMID 31952355, 2020). "Immunohistochemistry and RT-PCR analysis showed that CLDN-1 is either reduced or undetected in adenocarcinomas." (PMID 31952355, 2020). "The patients with elevated CLDN1 expression but with low SLUG expression had longer overall survival and longer disease-free survival than other adenocarcinoma patients." (PMID 32754286, 2020).
inflammation (7 papers, 2015 to 2023). Aberrant reaction of the microcirculation characterized by movement of fluid and leukocytes from the blood into extravascular tissues. "Still, studies have also found that both declines of tight junction proteins (like ZO-1, claudin-1, occludin) and increasing permeability (leaky gut) appear forward to severe gut inflammation." (PMID 36101343, 2022). "Additionally to colonic inflammation, CB0313.1 also reduced the colon permeability by upregulating the tight junction (TJ) proteins (claudin-1 and occludin) and contributed to a decreased circulating endotoxin level." (PMID 27123997, 2016).
intestinal diseases (5 papers, 2019 to 2025). "In intestinal diseases such as UC, the barrier function is compromised, with decreased expression of tight junction proteins (e.g., ZO-1, occludin, claudin-1), leading to increased intestinal epithelial permeability." (PMID 39940311, 2025). "Among these, tight junctions such as claudin-1 (CLDN-1) and OCLN proteins, are designated as bearing the most workload, with compromised function resulting in the pathogenesis of various intestinal diseases." (PMID 39334703, 2024). "Since CPE complexes are formed in the intestines, where intestinal proteases are present, it is possible that CLDN-1-mediated protease resistance helps to protect the CPE large complexes, and thus enhance CPE activity, during intestinal disease." (PMID 31601044, 2019). "Despite the fact that a decreased expression of Claudin-1 has been related with an increased permeability in intestinal disorders, there seems not to be a clear pattern for Claudin-3 expression, which may or may not be affected." (PMID 32098336, 2020).
metabolic disorders (5 papers, 2021 to 2025). "Additionally, the improvement of the intestinal barrier function plays an important role in attenuating metabolic diseases, with upregulating claudin 1, GLP1, IL-10, occludin 1, and ZO-1 expressions." (PMID 34579087, 2021). "In summary, PPSP could alleviate metabolic diseases by improving intestinal barrier function with upregulating GLUT4, GPR43, NLCR3, p38 MAPK, TRAF6-mediated signaling pathways and the expressions of claudin 1, GLP1, IL-10, occludin 1, and ZO-1." (PMID 34579087, 2021).
bacterial infection (4 papers, 2020 to 2025). "In addition to mucoprotein, Claudin-1, and Occludin proteins are the backbones that mainly constitute the tightly linked chains that reduce the uptake of toxins by the organism during pathogenic bacterial infections." (PMID 37138630, 2023). "S. aureus DSM20491 live bacterial infection revealed a decrease in the Claudin-1 signal compared to not treated infected tissues." (PMID 37111709, 2023).
gastrointestinal disorders (2 papers, 2024). "Studies have linked the decreased expressions of Claudin-1, Occludin, and ZO-1 with gastrointestinal disorders where the intestinal barrier is compromised." (PMID 38516705, 2024).
kidney diseases (2 papers, 2023 to 2024). "In this regard, the regulatory mechanism by which repressed Sirt1 augmented Claudin-1 is considered significant for establishing the potential of diagnostic markers and/or therapeutic targets of the Sirt1/Claudin-1 axis in kidney diseases." (PMID 38587753, 2024).
nervous system diseases (2 papers, 2020 to 2021). "We examined Claudin 1, Claudin 3, Claudin 5, Occludin and ZO-1 in 31 ALS-CP samples compared to 15 non-neurologic disease controls." (PMID 32586411, 2020). "CLDN-1 and CLDN-3 are the key components of tight junctions in blood brain barrier, and their abnormal function is one of the main reasons for the occurrence and development of nervous system diseases." (PMID 34008771, 2021).